ZXDA (zinc finger X-linked duplicated A)
Description:
Cooperates with CIITA to promote transcription of MHC class I and MHC class II genes.
Synonyms: ZNF896
Tractability: PROTAC: ubiquitination databases record sites on it.
Gene: Protein-coding gene on chromosome X (57,905,430 to 57,910,458, reverse strand). Ensembl gene ENSG00000198205.
Subcellular location: Nucleus
Subcellular location (Human Protein Atlas): Nucleoplasm
Gene Ontology:
Molecular function: C2H2 zinc finger domain binding; protein binding; transcription coactivator activity; transcription coregulator activity
Biological process: positive regulation of DNA-templated transcription; regulation of transcription by RNA polymerase II
Cellular component: nucleus
Homologues: Orthologues: chimpanzee ZXDA (98% identical), tropical clawed frog zxdc (47% identical), zebrafish si:dkey-156n14.3 (41% identical), Drosophila melanogaster ci (13% identical), Drosophila melanogaster lmd (12% identical), zebrafish zic6 (12% identical), Drosophila melanogaster opa (12% identical), Caenorhabditis elegans tra-1 (11% identical), Caenorhabditis elegans ref-2 (8% identical), Caenorhabditis elegans ztf-14 (8% identical). Paralogues in human: ZXDB (97% identical), ZXDC (56% identical), GLI2 (17% identical), GLI3 (17% identical), GLIS3 (15% identical), GLI1 (14% identical), GLIS1 (14% identical), ZIC2 (14% identical), ZIC3 (14% identical), ZIC1 (13% identical), ZIC5 (13% identical), GLIS2 (12% identical), and 2 more.
Diseases named in the same sentence as ZXDA in open-access papers:
ZXDA is named in the same sentence as 2 diseases in open-access papers, as found by Europe PMC text mining. Sharing a sentence is not in itself a finding about the gene and the disease. The quoted sentences say what the papers report.
muscular atrophy (1 paper, 2022). The loss of muscle tissue due to inactivity or disease. "Mutants of FBXO38 found in patients with muscular atrophy interacted with ZXDA/B more strongly, especially after MLN4924 treatment." (PMID 35813202, 2022).
ZXDA also shares sentences with these, for which no sentence is quoted: cancer (1 paper).